IL10 (interleukin 10)
Diseases named in the same sentence as IL10 in open-access papers (continued):
Sharing a sentence is not in itself a finding about the gene and the disease.
infection (continued). "Moreover, in IL-10−/− mice, Hh-infection induced pathogenic Hh-specific IL-17+IFN-γ+ Th17/Th1 cells, probably because of the inability of Tregs to restrain colitogenic Th17 cells in Hh-positive IL-10−/− mice." (PMID 33550886, 2021). "Previous work on male genital schistosomiasis has shown that infection intensity, defined by seminal egg count, is strongly associated with elevated seminal cytokine concentrations including Th2 (IL-4), regulatory (IL-10), Th1 (IFN-γ) and pro-inflammatory (TNF-α) cytokines." (PMID 33737927, 2021). "Moreover, the therapeutic effect of combined lactoperoxidase and lactoferrin treatment on A. baumannii infection was attributed to a substantial elevation of IL-4 and IL-10 concentrations, which prevents infection-associated tissue damage." (PMID 33042864, 2020). "IL-2+ CD4+ T cells, especially IL-2+ CD4+ TCM cells, in the lung after infection were significantly associated with the vaccine-induced protection, whereas stronger IL-10 response and lower IL-2+ CD4+ T cells also contributed to the inferior protection of the DDA/TDB adjuvanted CMFO subunit vaccine." (PMID 33117374, 2020). "It is also unclear whether excessive IL-10 production is a byproduct of highly pathogenic infections or if increased IL-10 directly contributes to severe disease progression in humans." (PMID 32974217, 2020). "IL-10 production is linked to pathology in this model of infection." (PMID 33212818, 2020). "While in the colon and duodenum the luminal C. coli loads were comparable, the pathogen burdens were approximately two and even four log orders of magnitude higher in the ileum and stomach, respectively, in TLR4-deficient IL10-/- as compared to IL10-/- counterparts, on day 21 post-infection." (PMID 32443576, 2020). "Results showed that A. baumannii-induced AKT phosphorylation was unimpaired in IL-10-deficient macrophages, compared to WT cells, but showed slightly enhanced activation in IL-10-deficient cells after long infection times." (PMID 32153580, 2020). "However, strict control of inflammation is mandatory, as IL-10-deficient mice succumb from an unrestrained cytokine storm within 10 days of a Trypanosome brucei infection." (PMID 32655552, 2020). "The seeming contradiction between our findings and those reported by Yao and colleagues during acute LCMV infection can be explained by the predominant focus of that study on CD8+ T cell responses and the fact that IL-10 determines susceptibility to infection only in chronic LCMV infection models." (PMID 32321759, 2020). "The pronounced IFN response associated with a reduction of tolerogenic factors (IL-10 and B7-H3) suggests the placenta retains the ability to induce an intense antiviral network, which could limit the fetal infection during pregnancy." (PMID 32983090, 2020). "IL-4/IL-10 double-deficient mice develop highly polarized Th1-type cytokine responses, exhibited by rapid weight loss during egg production and 100% acute mortality by week 9 post-infection." (PMID 32132991, 2020). "TLR2-deficient mice expressed significant IL-10 following infection with Δhly." (PMID 32634175, 2020). "The inability of a VL patient to mount protective Th1 immune response (IL-2 IFN-γ, TNF- α), exacerbates the pathogenicity and in some cases results in resistance to drug.There are reports that when over expression of IL-10, render the resistant mice, susceptible to infection." (PMID 32555598, 2020). "Since myeloid cells could also be a source of IL-10 in infected animals, we included in subsequent experiments myeloid-specific IL-10-deficient (LysM-IL-10-/-) mice and compared their infection parameters to TgAlbCre-IL10-/- and WT controls." (PMID 32012211, 2020). "Also, systemic levels of IL-10 appear to facilitate bacterial persistence and dissemination within the host during infections caused by intracellular bacteria or by pathogens that modulate the inflammatory responses." (PMID 32117251, 2020).
infection (continued). "Therefore, high levels of IL‐17A, IL‐10 and sE‐selectin identified both patients at higher risk of persistent bacteraemia and patients with endovascular reservoirs of infection despite surveillance blood cultures rapidly turning negative." (PMID 32082571, 2020). "At the same time, downregulation of Th2 cytokines, such as IL4/IL13, as well as IL10 and TGFβ, which are primarily associated with tissue repair and extracellular matrix composition, was observed during the late stage of infection, especially in infected fish at 11°C." (PMID 32695119, 2020). "However, initial response can be observed as early as 2 days post infection with the induction of interleukin-10 (IL-10) associated with the generation regulatory T cells." (PMID 32080317, 2020). "In contrast, IL-12/IL-10 double-deficient mice with highly polarized Th2-type cytokine responses develop increased hepatic fibrosis and mortality during the chronic stages of infection." (PMID 32132991, 2020). "However, many immunoregulatory molecules and pathways, most notably those associated with interleukin-10 (IL-10) production, are activated following infection, which can suppress anti-parasitic CD4+ T cell functions." (PMID 32101732, 2020). "In an experimental model of chronic tuberculosis infection, a monoclonal antibody targeting IL-10R was administered 90 days into the infection, as this time point was before loss of control of infection and when IL-10 levels peaked in this model, and weekly thereafter." (PMID 32425944, 2020). "In addition, IL‐10 can also promote the healing process of injured tissues caused by infection or inflammation (Ouyang, Rutz, Crellin, Valdez, & Hymowitz, 2011)." (PMID 31319442, 2019). "Collectively, these data indicate that following acute immune stimulation, plasmablasts/plasma cells represent an important source of the anti-inflammatory cytokine IL-10, that can dampen autoimmune and infection driven inflammation but can also increase susceptibility to infection." (PMID 31214168, 2019). "We hypothesised that infection of IL-10 signalling-deficient mice with whipworms caused caecal dysbiosis and the overgrowth of opportunistic bacteria from the microbiota." (PMID 30640950, 2019). "Interestingly, IL-10 induction has been associated with the early phases of an infection whereas our data links elevated IL-10 levels to long-term colonisation / persistence." (PMID 31338112, 2019). "Simvastatin also favors IL-10 secretion and activated lymphocyte apoptosis, both of which are relevant phenomena that could inhibit adequate infection control, however, they could also mitigate the damage caused by excessive inflammation." (PMID 31616387, 2019). "For this reason, we employed the well-characterized BALB/c model of CL by L. amazonensis in which animals are susceptible to infection and develop chronic lesions in the presence of IL-4 and IL-10, in contrast with C57BL/6 mice, where these two Th2-characteristic cytokines seem to have no relevance." (PMID 31739549, 2019). "On the other hand, IL-10 is associated with macrophage deactivation and progressive infection." (PMID 31867285, 2019). "However, host-mediated inflammation resulting from an infection or genetic predisposition, such as mutations in IL-10, increases available oxygen." (PMID 30640950, 2019). "Interferon-gamma (IFN-γ) and tumor necrosis factor (TNF) -α and -β, from the Th1 profile, are known to be involved in the resistance and elimination of the parasites, while Th2 cytokines such as IL-4 and IL-10 are linked to susceptibility to infections by Leishmania." (PMID 31131262, 2019). "In addition to its negative regulation of inflammation and autoimmunity, IL-10 production from Bregs also promotes susceptibility in the early stages of infections with viruses, bacteria, helminths, or parasitic protozoa." (PMID 31474988, 2019).
infection (continued). "Although there is no direct relation between them, both are parameters known to be associated with severity of VL, since high levels of IL-10 in the active phase of the disease may contribute to parasite proliferation and a successful infection." (PMID 30913261, 2019). "Importantly, the inflammatory changes required both infection with H. hepaticus and neutralization of IL-10R signaling, with very few changes being seen in mice with H. hepaticus infection alone or loss of IL-10 alone." (PMID 29203542, 2018). "Thus, excessive IL-10 production can inhibit proinflammatory response to several pathogens, resulting in uncontrolled infection and deficient immune response, which are characteristics that are often observed in DS." (PMID 30186038, 2018). "Similar to TGF-β, IL-10 is an anti-inflammatory cytokine related to infection susceptibility." (PMID 29662478, 2018). "Our data indicate that IL-10-producing Tr1 cells, Treg cells and CD8+ T cells are all capable of co-expressing LAG3 and CD49b in vitro following differentiation under IL-10-inducing conditions, and in vivo following pathogenic insult or infection in the pulmonary mucosa." (PMID 30510554, 2018). "Higher levels of IL-10 mRNA (P = 0.007) and protein measured 24 hours post-operatively (P<0.0001) were most strongly associated with the development of a subsequent infection." (PMID 30212506, 2018). "Lastly, one SNP was associated with IL-10 level at the height of infection, on chromosome 4." (PMID 30463512, 2018). "In EBV+HIV+ patients, EBV active infection could induce the synthesis of virus-encoded IL-10 (BCRF1) as well as that of human IL-10 and IL-2 through the action of EBV LMP-1 and LMP-2 proteins that, in turn, could activate the NF-κB pathway." (PMID 30337929, 2018). "We conclude that the production of IL-10 improves host survival during infections caused by extracellular or highly inflammatory bacteria, however, it is detrimental during infections caused by intracellular bacteria or bacterial pathogens that modulate the inflammatory response." (PMID 30279680, 2018). "In this mini-review, we will discuss whether the role of IL-10 during infections caused by major antibiotic susceptible bacteria applies to major MDR-bacterial infections." (PMID 30279680, 2018). "In addition, we saw no changes in tumor necrosis factor (TNF-α), IL-8, CXC chemokine ligand 2 (CXCL2), or IL-10 signaling in MRP1 knockdown cells either before or after infection as measured by an enzyme-linked immunosorbent assay (ELISA)." (PMID 29976647, 2018). "Greater post-operative Interleukin-10 production is associated with later infection." (PMID 30212506, 2018). "In summary, C. jejuni-infection induced less clinical signs and apoptosis, but more distinct colonic pro- and anti-inflammatory immune as well as regenerative cell responses in Nod2 deficient IL-10−/− as compared to IL-10−/− control mice." (PMID 28752081, 2017). "IL-10 encoding mRNA was significantly increased after 120 h post infection in ileum <liver <spleen." (PMID 28824622, 2017). "Research suggests that pathogens might cause high IL-10 expression to better sustain the infection process." (PMID 28793052, 2017). "Interleukin 10 (IL-10), produced by dendritic cells (DCs) and regulatory T cells (Tr1), acts to suppress antiparasitic immune mechanisms in human VL, with IL-10 deficiency protecting against infection and blockade of IL-10 signaling, enhancing antiparasitic immunity." (PMID 28493863, 2017). "Notably, splenic IL-10 concentrations were unaffected upon bacterial re-colonization and/or pathogenic infection (n.s.)." (PMID 28413453, 2017). "This suppressive activity of CD11c+ APC-derived IL-10 during M. tuberculosis infection is in line with a recent study showing that reduced IL-10 production by APC during infection of DAP12-deficient mice correlated with increased Th1 cell activation and enhanced host protection." (PMID 28584007, 2017).
infection (continued). "Finally, HO-1 expression during F. hepatica infection was associated with TGFβ and IL-10 levels in liver and peritoneum, suggesting that HO-1 controls the expression of these immunoregulatory cytokines during infection favoring parasite survival in the host." (PMID 28798750, 2017). "In contrast, a recent study that utilized cell-specific deletion of Il10 expression in vivo suggests that a reduction of bacterial burden in lungs of IL-10-deficient mice during the chronic phase of infection (day 60) is attributable to IL-10 produced by CD4+ T cells rather than myeloid or B cells." (PMID 29230217, 2017). "Importantly, IL-10−/− mice that received B cells also showed a significant increase in clinical score and weight loss; however, the survival rate at day 14 post infection was better than IL-10−/− mice that received T cells." (PMID 28824622, 2017). "Interestingly, the down regulation is favorable as IL-10 and Th2 response are associated with susceptibility to infection and disease enhancement." (PMID 29133871, 2017). "The IL-10, in our infection model, has been associated to pathogenesis." (PMID 28848541, 2017). "This increased susceptibility to infection and inflammation may also be further amplified by the observed lower IL-10 levels in the lymphoid compartments with subsequent consequences for anti-inflammatory Treg-mediated responses." (PMID 28469619, 2017). "Early measures of circulating TNF-α/IL10 ratio may be a previously unidentified biomarker associated with burn injury severity and predictive of the risk of hypersusceptibility to repeated infections." (PMID 27761434, 2016). "Consequently, dysregulation of IL-10 is linked with susceptibility and an impaired clinical course of numerous infections in mouse models and in humans." (PMID 27465248, 2016). "However, IL-27 impairs control of acute mouse hepatitis replication and associated pathology following infection of the CNS and this phenotype is associated with reduced accumulation of IL-10+ CD4+ T cells." (PMID 27926930, 2016). "However, IL-10-deficient mice exhibit increased inflammatory processes and frequently develop severe immune-mediated pathology during various Plasmodium species infections (5, –, 8)." (PMID 26459508, 2016). "Given the known immune modulating effects of GXM and the strong association between serum GXM titer and IL-10 concentration observed in this cohort, it is plausible that this may be a direct consequence of disseminated infection with C. neoformans." (PMID 26768248, 2016). "Although IL-10 and TGFβ have been reported to contribute to VL pathogenesis, information regarding the cellular subtypes associated with the elevation of these cytokines during infection remains limited." (PMID 26829554, 2016). "We therefore propose that early plasma TNF-α/IL-10 cytokine ratio may serve as a useful, risk predictor for infection hypersusceptibility in severe trauma in general." (PMID 27761434, 2016). "While static images revealed that IL-10-producing cells were located near areas of virus-infected cells, they could be 1) engaged and motionless, 2) motile at the perimeter of infection, or 3) only transiently associated with the borders of lesions." (PMID 26991092, 2016). "This study aims to evaluate whether the TNF-α/IL-10 ratio, a cytokine marker of the balance between key pro- to anti-inflammatory levels, would predict susceptibility to multiple infections." (PMID 27761434, 2016). "The intracardiac route is responsible for the development of Th2 immune response that is characterized by IL4 production and increased levels of IgG1 and is associated with IL10 production by Treg cells, thus allowing the establishment of a persistent infection." (PMID 26969511, 2016).
infection (continued). "Specific HPV proteins, such as E2, E6, and E7, have been reported as associated with certain cytokine dysfunctions, and in HPV-infected cervical epithelial cells, the HPV E2 protein has been shown to induce IL-10 activity and to cause immune suppression and persistence of the infection." (PMID 26257474, 2015). "Interestingly, Breg cell development can also be seen during the infections caused by Leishmania major; IL-10-producing B cells were critical for the development of unprotective TH2 responses and susceptibility to infection." (PMID 26236565, 2015). "Pretreatment of mice with exosomes derived from L. major and L. donovani resulted in exacerbated infection and pathogenesis in vivo, associated with enhanced IL-10 production and a skewed Th2 response, preventing parasite expulsion as a type 1 response is normally required for clearance." (PMID 26433251, 2015). "Since IL-10-/- mice infected with Pb18 have been shown to control disease more efficiently than WT mice, the lower IL-10 amounts associated to the depletion of the Treg cell population has possibly contributed to the augmented resistance to infection observed in the animals treated with anti-CD25." (PMID 26512987, 2015). "Furthermore, IL-10 deficiency (IL-10-/-mice) reversed the immunosuppressive effects of salivary nucleosides during infection; however, ablation of IL-10 promoted significant tissue damage independently of nucleoside treatment." (PMID 25849562, 2015). "Notably, following inoculation of the parasite microvesicles and subsequent infection with T. cruzi, mice develop heightened cardiac parasitism and increased inflammatory infiltrates associated with higher levels of IL-4 and IL-10." (PMID 26433251, 2015). "Growing research evidence underscores the paramount importance of investigating the role of IL-10 during soil-transmitted helminthiases as it may increase susceptibility for these infections." (PMID 25888883, 2015). "High level of IL-10 secretion may be associated with poor outcome after trauma, and identification of those patients likely shows sensitivity to infection, may enable novel targeted therapy in near future." (PMID 26561011, 2015). "Because salivary nucleosides potentiated IL-10 production and mediated susceptibility to the infection, we addressed whether the CD4+CD25-expressing Treg markers in the CD4+CD25-population could contribute to nucleoside-induced IL-10 production." (PMID 25849562, 2015). "This “autoregulatory” population consists predominantly of IL10/IFNγ co-producing cells that express the canonical Th1 transcription factor Tbet and appear to be short-lived in the periphery, exhibiting a strong association with recent infection." (PMID 26182204, 2015). "Moreover, high level of IL-10 expression has been reported in mice vaccinated with Shiga toxins (Stxs) fusion proteins from EHEC, demonstrating that production of IL-10 is a natural response against E. coli pathogenic infection." (PMID 26835434, 2015). "Besides the high levels of IL-4 expected with this infection we also found elevated IL-10 levels associated with a downregulation of proinflammatory cytokines." (PMID 26090422, 2015). "We could speculate that once parasitized with one species, children who build tolerance through higher levels of IL-10 could be more susceptible to infection with another species." (PMID 25888883, 2015). "IL-10 production by T cells potentially leads to overproduction of anti-inflammatory cytokines by compensatory anti-inflammatory response and eventually increases risk of secondary infection and inaccurate prognosis." (PMID 26446682, 2015). "infection induces anti-inflammatory Th2 responses and is also associated with an immunoregulatory immune response, defined by elevated levels of interleukin (IL)-10 and transforming growth factor-β (TGF-β)." (PMID 25309052, 2014).